ACOX2 (acyl-CoA oxidase 2)
Description:
Involved in peroxisomal beta-oxidation of branched-chain fatty acids (BCFAs) and bile acids intermediates. Catalyzes the initial and rate-limiting dehydrogenation step that removes two hydrogen molecules and introduces a trans double bond between the alpha and beta carbons of the acyl CoA molecules while generating hydrogen peroxide as a by-product. Oxidizes its substrates in a stereospecific way and can only desaturate isomers carrying (2S)-methyl groups (By similarity). In brown adipose tissue peroxisomes, mediates beta-oxidation of monomethyl branched-chain fatty acids with iso configuration (mmBCFAs) as part of a substrate synthesis and oxidation cycle fueled by FASN-dependent de novo mmBCFA synthesis. The mmBCFA catabolism is coupled to AMPK activation and mitochondrial ATP production as a thermogenic adaptation mechanism to maintain the body temperature in cold environment (By similarity). Metabolizes multi-methyl-branched fatty acyl-CoA esters such as (2S)-pristanoyl-CoA, displaying redundancy with ACOX3. In the liver, mediates side-chain beta-oxidation of C27 bile acyl-CoA intermediates carrying a (25S)-methyl group to yield 24,25-trans unsaturated derivatives as part of peroxisomal bile acid synthesis pathway. Can oxidize straight-chain fatty acyl CoAs such as C10-CoA and C16-CoA with low efficiency.
Synonyms: THCCox; BRCACOX; BRCOX; BCOX; CBAS6
Tractability: PROTAC: its protein half-life has been measured.
Gene: Protein-coding gene on chromosome 3 (58,504,544 to 58,537,387, reverse strand). Ensembl gene ENSG00000168306.
Subcellular location: Peroxisome
Subcellular location (Human Protein Atlas): Vesicles; Cytosol
Pathways (Reactome):
Metabolism: Beta-oxidation of pristanoyl-CoA; Synthesis of bile acids and bile salts via 7alpha-hydroxycholesterol
Protein localization: Peroxisomal protein import
Gene Ontology:
Molecular function: 3alpha,7alpha,12alpha-trihydroxy-5beta-cholestanoyl-CoA 24-hydroxylase activity; protein binding; fatty acid binding; flavin adenine dinucleotide binding; long-chain fatty acyl-CoA oxidase activity; protein homodimerization activity; acyl-CoA oxidase activity; FAD binding; medium-chain fatty acyl-CoA oxidase activity; oxidoreductase activity; oxidoreductase activity, acting on the CH-CH group of donors; pristanoyl-CoA oxidase activity
Biological process: bile acid biosynthetic process; fatty acid beta-oxidation using acyl-CoA oxidase; very long-chain fatty acid metabolic process; fatty acid beta-oxidation; fatty acid metabolic process
Cellular component: peroxisome; cytosol; peroxisomal matrix
Genetic constraint (gnomAD): Loss-of-function variants: 63 observed, 85.05 expected, observed/expected ratio (o/e) 0.74, 90% interval 0.6 to 0.91. The upper end of that interval is the gene's LOEUF score, 0.91, which puts it in group 3 of 6, group 1 being the genes least tolerant of losing a copy. Missense variants: 836 observed, 925.46 expected, observed/expected ratio (o/e) 0.9, 90% interval 0.85 to 0.96. Synonymous variants: 317 observed, 359.36 expected, observed/expected ratio (o/e) 0.88, 90% interval 0.8 to 0.97.
Gene-disease validity (ClinGen):
ClinGen rates the evidence that ACOX2 causes each of these diseases.
congenital bile acid synthesis defect 6 (autosomal recessive): Definitive.
Homologues: Orthologues: chimpanzee ACOX2 (99% identical), macaque ACOX2 (96% identical), pig ACOX2 (81% identical), dog ACOX2 (79% identical), rabbit ACOX2 (77% identical), rat Acox2 (74% identical), mouse Acox2 (73% identical), guinea pig ACOX2 (72% identical), tropical clawed frog acox2 (53% identical), Caenorhabditis elegans acox-1.1 (36% identical), Caenorhabditis elegans acox-1.4 (36% identical), Caenorhabditis elegans acox-1.2 (35% identical), and 11 more. Paralogues in human: ACOX1 (44% identical), ACOX3 (24% identical), ACOXL (18% identical), ACADVL (14% identical), ACAD9 (13% identical), ACADSB (13% identical), IVD (12% identical), ACADM (12% identical), ACAD10 (11% identical), ACADL (11% identical), ACAD8 (11% identical), ACADS (11% identical), and 2 more.
Diseases named in the same sentence as ACOX2 in open-access papers:
ACOX2 is named in the same sentence as 52 diseases in open-access papers, as found by Europe PMC text mining. Sharing a sentence is not in itself a finding about the gene and the disease. The quoted sentences say what the papers report.
hepatocellular carcinoma (9 papers, 2015 to 2025). A malignant tumor that arises from hepatocytes. "RNA extracts from a panel of breast cancer cell lines, as well as HepG2 hepatocellular carcinoma cells, were analyzed for the full length and variant ACOX2 transcripts by qRT-PCR." (PMID 26183823, 2015). "A variant transcript of ACOX2 has been detected in hepatocellular carcinoma (HCC) where it was suggested to play a role in tumor progression." (PMID 26183823, 2015). "The peroxisomal enzyme Acyl-CoA oxidase 2 (ACOX2) has been postulated as a tumor suppressor in hepatocellular carcinoma via the positive regulation of PPARα." (PMID 35954274, 2022). "In addition to NSCLC, ACOX2 has also been shown to be dysregulated in various cancers, including breast cancer, prostate cancer, and hepatocellular carcinoma, and targeting peroxisomes is an emerging potential therapeutic approach including NSCLC." (PMID 36980522, 2023). "Some of the genes in these pathways include ALAS1, ACAA1, and ACOX2 which are negatively correlated with recurrence-free survival in patients with hepatitis B-related (HBV) hepatocellular carcinoma (HCC)." (PMID 36768794, 2023). "On the other hand, ACOX2, known to be related to ACOX3, is proposed as a promising prognostic marker in hepatocellular carcinoma and breast carcinomas." (PMID 35335125, 2022). "Besides the upregulation of PPARα in hepatoma cell lines with ACOX2 overexpression, no mechanistic link between the two proteins has been explored." (PMID 35954274, 2022).
breast carcinoma (7 papers, 2015 to 2025). "Using RNA-seq data, we found that this ACOX2 variant, ACOX2-i9, is present in a subset of human breast cancers." (PMID 26183823, 2015). "This is consistent with ACOX2-i9 expression in ER+ cancers being associated with luminal A breast cancer subtype." (PMID 26183823, 2015). "Ribonucleic acid-sequencing (RNA-seq) data from breast cancer samples was used to identify an intronic start variant transcript of Acyl-CoA oxidase 2, ACOX2 (ACOX2-i9)." (PMID 26183823, 2015). "In this study we have shown that a variant (shorter) transcript of ACOX2, identified by RNA sequencing, translates into a protein detectable in several breast cancer cell lines, as well as the HCC cell line, HepG2." (PMID 26183823, 2015). "As this variant transcript is represented in all the clinical breast cancer subgroups, and mainly confined to the tumor, ACOX2-i9 could be a possible independent target for therapy." (PMID 26183823, 2015). "In human breast cancer, the expression of the ACOX2 gene was significantly decreased (log2 (fold change) = −2.21, p = 6.34 × 10−14)." (PMID 40218347, 2025). "The expression and translation of ACOX2-i9 into a 25 kDa protein was demonstrated in HepG2 cells as well as in several breast cancer cell lines." (PMID 26183823, 2015). "In order to identify a possible protein product of ACOX2-i9, protein was extracted from the breast cancer cell lines and HepG2 cells and probed with a monoclonal antibody raised against the far C-terminal (100aa) domain of ACOX2." (PMID 26183823, 2015). "In a genome wide screen aimed at identifying alternative transcripts in breast tumors using RNA-seq, the presence of an alternative mRNA transcribed from the ACOX2 locus in breast cancers was identified." (PMID 26183823, 2015). "Specifically, we sought to estimate differences in the expression of two suspected good prognosis genes (ACOX2 and MUC1) and six suspected poor prognosis genes (FAM177A1, GSTT2, PSPH, PSPHL, SQLE, and TYMS) by race, and to examine their associations with risk of breast cancer recurrence." (PMID 29228969, 2017). "Together these data indicate that the expression of ACOX2-i9 is effected by ESR1 stimulation and inhibition in breast cancer cell lines." (PMID 26183823, 2015). "Alternatively, ACOX2-i9 expression may mark a set of better prognosis ER+ cancers (ie luminal A breast cancers) regardless of hormonal therapy." (PMID 26183823, 2015).
liver cancer (5 papers, 2021 to 2025). An epithelial or non-epithelial malignant neoplasm that arises from the liver. "Knockout studies have shown that loss of Acox2 can lead to liver cancer in mice, underscoring the liver-protective role of OATD-01, which elevated the expression of this gene." (PMID 40510344, 2025). "Previous research has shown that ACOX2 deficiency can be detected in liver cancer 29 and non-small cell lung cancer 30, indicating a poor prognosis of these patients." (PMID 38706909, 2024). "A comprehensive study, integrating TCGA datasets, clinical samples, and both in vivo and in vitro experiments, suggests that ACOX2 impedes the progression of liver cancer through the PPARα pathway." (PMID 38279987, 2024). "Overall, our results suggest that Acox2 is a regulator for protein post-translational modifications, mainly Kcr, that play important roles on metabolic homeostasis and liver cancer progression in mice." (PMID 35351852, 2022). "In conclusion, we demonstrated a PRG ACOX2, and its overexpression reduced the proliferation and metastasis of liver cancer in vitro and in vivo through PPARα pathway." (PMID 33414412, 2021). "Further, we detected the expression of ACOX2 in liver cancer cells and normal human hepatocyte cells." (PMID 33414412, 2021). "Cell Counting Kit-8 assay, wound healing, and transwell migration assay were applied to evaluate the impact of ACOX2 overexpression on the proliferation and migration abilities in two liver cancer cell lines." (PMID 33414412, 2021). "In our study, we found that ACOX2 was significantly downregulated in liver cancer tissues and cells." (PMID 33414412, 2021). "Then, we performed the wound-healing experiments on the liver cancer cells with control, vector, and ACOX2 overexpression and found that the migration ability was significantly decreased upon ACOX2 overexpression." (PMID 33414412, 2021). "Acox2 knockout (−/−) mice spontaneously developed liver cancer with marked lymphocytic infiltrate." (PMID 35351852, 2022). "We next verified the expression of ACOX2 in liver cancer tissues." (PMID 33414412, 2021). "However, more studies are needed to clarify the molecular mechanism responsible for the roles of ACOX2 in liver cancer." (PMID 33414412, 2021). "Further, the expression of PPARA is positively correlated with ACOX2 in liver cancer." (PMID 33414412, 2021). "So, ACOX2 may regulate the PPARα pathway to inhibit the proliferation of liver cancer." (PMID 33414412, 2021). "Also, PPARα and ACOX2 are strongly correlated in the liver cancer tissues." (PMID 33414412, 2021). "To determine the function of ACOX2 in liver cancer, we first overexpressed ACOX2 in HepG2 and SMCC-7721 cells and found that overexpression of the ACOX2 inhibits the proliferation of the HepG2 and SMCC-7721 cells." (PMID 33414412, 2021). "The results showed that the expression of ACOX2 in liver cancer tissues was much lower than that from the adjacent noncancerous tissues." (PMID 33414412, 2021). "However, the roles of ACOX2 in liver cancer have not been well characterized." (PMID 33414412, 2021). "We found that three genes ACOX2, ALDH8A1, and SCP2 were not reported in-depth in liver cancer." (PMID 33414412, 2021).
breast tumors (4 papers, 2015 to 2021). "The clinical/biological relevance of this variant transcript of ACOX2 was further studied in an independent set of 113 breast tumor samples from patients from the well characterized MicMa cohort for which long-term clinical follow up data were available." (PMID 26183823, 2015). "Amongst these were 4 extensively studied splicing isoforms (MYO6, TPD52, IQCG, and ACOX2) identified to be amongst the 5 most important isoforms differentially expressed between ER+HER2− and ER-HER2 primary breast tumors." (PMID 33050927, 2020).
prostate carcinoma (4 papers, 2012 to 2024). A carcinoma that arises from epithelial cells of the prostate gland. "The expression of ACOX2 in prostate cancer was lower than in benign prostate tissues (P < 0.01)." (PMID 38706909, 2024). "Also directly repressed by AR is ACOX2, a branched-chain acyl-CoA oxidase enzyme that takes part in the degradation of long branched fatty acid and bile acid intermediates in peroxisomes and is down-regulated in castration-resistant prostate cancer." (PMID 22849360, 2012).
Ataxia (3 papers, 2017 to 2025). Ataxia refers to impaired coordination of voluntary muscle movement. "It has recently been reported that a defect in ACOX2 leads to liver fibrosis, mild ataxia, and cognitive impairment." (PMID 28411018, 2017).
liver disease (3 papers, 2022 to 2025). "In ACOX2 deficiency there is evidence that liver disease may be improved by treatment with UDCA." (PMID 40847535, 2025). "While this finding points to the potential regulatory role of ACOX2 in hepatic metabolic homeostasis, further studies are needed to establish mechanistic links and their implication in human liver disease." (PMID 40943222, 2025). "Targeting ACOX1 and ACOX2 could be considered a viable strategy for managing both liver disease and peroxisomal disorders." (PMID 40943222, 2025). "The existence of a positive correlation between ACOX2 and HNF4A expression in inflammatory liver diseases supports the hypothesis that ACOX2 expression can be controlled by HNF4α, which is consistent with the predominant ACOX2 expression in hepatocytes." (PMID 36552746, 2022).
liver fibrosis (3 papers, 2017 to 2025). "Further, ACOX2 deficiency has been linked to an increased risk of developing liver fibrosis, but its role in pulmonary fibrosis is unknown." (PMID 36267568, 2022).
lung carcinoma (3 papers, 2019 to 2022). "As ACOX2 was suggested to be elevated at the mRNA level in over 10% of NSCLC, we undertook an analysis of this gene in NSCLC to determine if it had any potential utility as a biomarker in lung cancer at both mRNA and protein level." (PMID 35999530, 2022).
non-small cell lung carcinoma (3 papers, 2022 to 2024). A group of at least three distinct histological types of lung cancer, including non-small cell squamous cell carcinoma, adenocarcinoma, and large cell carcinoma. "ACOX2 expression is significantly reduced in the vast majority of non-small cell lung cancer (NSCLC) patients." (PMID 38279987, 2024).
renal fibrosis (3 papers, 2021 to 2023). A final common manifestation of a wide variety of chronic kidney diseases characterized by glomerulosclerosis and tubulointerstitial fibrosis. "Consistent with the reports, our study showed that the gene expression of FAO-related key metabolic enzymes (CPT1A, CPT2, and ACOX2) and the FAO transcription regulatory factors (PPARα and PGC1α) were markedly decreased in renal fibrosis induced by I/R." (PMID 35526054, 2022).
cardiac tumor (2 papers, 2018 to 2024). "We previously reported a functional mutation ACOX2 (R409H), which is potentially associated with decreased β-oxidation of fatty acids in the cardiac tumor tissue." (PMID 30062063, 2018). "Besides, ACOX2 deficiency also presents in primary malignant cardiac tumors and estrogen receptor positive breast cancer." (PMID 38279987, 2024). "Although we fail to provide solid evidence to support that germline FH (E404D) and ACOX2 (R409H) are a direct cause of tumorigenesis in the heart, our results suggested that these two variants have combined effects on metabolic dysfunction in the cardiac tumor." (PMID 30062063, 2018).
cholestasis (2 papers, 2022 to 2023). Impairment of the bile flow caused by obstruction within the liver, or outside the liver in the bile duct system. "The genes regulated in all pathways, Cyp1a1, Cyp1a2, Cyp2a1, Cyp2b1, Cyp4a8, Cyp2c11, Rdh16, Alox15, Ephx2, Sult2a1, and Acox2, were the potential targets for ZYP treatment of cholestasis." (PMID 37881184, 2023). "Acox2 and Sult2a1 are essential genes in PPAR signaling and bile secretion, and studies have revealed a correlation between the expression of these genes and cholestasis." (PMID 37881184, 2023).
autoimmune conditions (1 paper, 2022). "All healthy controls (n = 74) and non-hematological patients without autoimmune conditions (n = 154) were tested negative for aCOX-2 Ab." (PMID 35927326, 2022).
cerebrotendinous xanthomatosis (1 paper, 2021). Cerebrotendinous xanthomatosis (CTX) is an anomaly of bile acid synthesis characterized by neonatal cholestasis, childhood-onset cataract, adolescent to young adult-onset tendon xanthomata, and brain xanthomata with adult-onset neurologic dysfunction. "The value of the method is illustrated by confirming the sterol phenotype of a patient suffering from ACOX2 deficiency, a rare disorder of bile acid biosynthesis, and in a plasma sample from a patient suffering from cerebrotendinous xanthomatosis, where cholesterol 27-hydroxylase is deficient." (PMID 33736801, 2021).
Cirrhosis (1 paper, 2021). A chronic disorder of the liver in which liver tissue becomes scarred and is partially replaced by regenerative nodules and fibrotic tissue resulting in loss of liver function. "We finally found that only ACOX2 was significantly correlated with cirrhosis (P < 0.05)." (PMID 33414412, 2021).
COVID-19 (1 paper, 2024). A disease caused by infection with severe acute respiratory syndrome coronavirus 2. "At the same time, we found that ACOX2 and PECR, as genes for fatty acid metabolism, may regulate the expression of SCD during the occurrence and development of COVID-19, thus affecting the occurrence and development of AMD." (PMID 38625951, 2024). "Therefore, we explored the common pathogenesis of AMD and SARS-CoV-2, and found that COVID-19 and AMD have five common differences in FAMRG, namely FASD1, HMGCS1, ACOX2, ACAT2 and PECR." (PMID 38625951, 2024). "Therefore, ACOX2 and PECR may regulate the expression of SCD during the development of COVID-19, thus affecting the occurrence and development of AMD." (PMID 38625951, 2024).
glioma (1 paper, 2020). A benign or malignant brain and spinal cord tumor that arises from glial cells (astrocytes, oligodendrocytes, ependymal cells). "Among these metabolic genes, most have not been reported to be associated with prognosis of glioma patients, and only ACOX2 is involved in the prognosis of breast cancer." (PMID 31897239, 2020).
liver dysfunction (1 paper, 2025). "Quinoa upregulates ACOX2 in the liver and reduces ALT and AST levels, indicating that ACOX2 may be another potential target for treating NAFLD liver dysfunction." (PMID 41306343, 2025).
multiple sclerosis (1 paper, 2022). A progressive autoimmune disorder affecting the central nervous system resulting in demyelination. "Sporadic non-IAA aCOX-2 Ab positive cases were observed among patients with related bone marrow failure diseases, multiple sclerosis, and type I diabetes, whereas no aCOX-2 Ab seropositivity was detected in the healthy controls, in patients with non-autoinflammatory diseases or rheumatoid arthritis." (PMID 35927326, 2022).
ovarian carcinoma (1 paper, 2025). A malignant neoplasm originating from the surface ovarian epithelium. "The dysregulation of ACOX2 may impact cellular metabolism and is implicated in various diseases, including ovarian cancer." (PMID 40430078, 2025). "Furthermore, we did not observe the prognostic impact of NAC1/ACOX2 in other histological subtypes of ovarian cancer in order to clarify whether our findings are ERON-specific." (PMID 40430078, 2025).
Perrault syndrome 1 (1 paper, 2019). Any Perrault syndrome in which the cause of the disease is a mutation in the HSD17B4 gene. "However, homozygous variants in HSD17B4 (D-bifunctional protein deficiency (MIM# 261515), Perrault syndrome 1 (MIM# 233400)) and ACOX2 (Bile acid synthesis defect, congenital (MIM# 617308)) have reliably been associated with monogenic diseases." (PMID 31533369, 2019).